ALPK1 (alpha kinase 1)
Description:
Serine/threonine-protein kinase that detects bacterial pathogen-associated molecular pattern metabolites (PAMPs) and initiates an innate immune response, a critical step for pathogen elimination and engagement of adaptive immunity. Specifically recognizes and binds ADP-D-glycero-beta-D-manno-heptose (ADP-Heptose), a potent PAMP present in all Gram-negative and some Gram-positive bacteria. ADP-Heptose-binding stimulates its kinase activity to phosphorylate and activate TIFA, triggering pro-inflammatory NF-kappa-B signaling. May be involved in monosodium urate monohydrate (MSU)-induced inflammation by mediating phosphorylation of unconventional myosin MYO9A. May also play a role in apical protein transport by mediating phosphorylation of unconventional myosin MYO1A. May play a role in ciliogenesis.
Synonyms: KIAA1527; LAK; FLJ22670; 8430410J10Rik; ROSAH
Tractability: Small molecule: a structure with a bound ligand is known.
Gene: Protein-coding gene on chromosome 4 (112,285,509 to 112,442,621, forward strand). Ensembl gene ENSG00000073331.
Subcellular location: Cytoplasm, cytosol; Cytoplasm, cytoskeleton, spindle pole; Cytoplasm, cytoskeleton, microtubule organizing center, centrosome; Cell projection, cilium
Subcellular location (Human Protein Atlas): Basal body; Centrosome
Pathways (Reactome):
Immune System: Alpha-protein kinase 1 signaling pathway; TAK1-dependent IKK and NF-kappa-B activation
Gene Ontology:
Molecular function: monosaccharide binding; protein binding; protein serine kinase activity; protein serine/threonine kinase activity; ATP binding
Biological process: cilium assembly; cytoplasmic pattern recognition receptor signaling pathway; innate immune response; positive regulation of canonical NF-kappaB signal transduction
Cellular component: centrosome; ciliary basal body; cilium; cytosol; spindle pole
Genetic constraint (gnomAD): Loss-of-function variants: 104 observed, 113.43 expected, observed/expected ratio (o/e) 0.92, 90% interval 0.78 to 1.08. The upper end of that interval is the gene's LOEUF score, 1.08, which puts it in group 4 of 6, group 1 being the genes least tolerant of losing a copy. Missense variants: 1,461 observed, 1,516.1 expected, observed/expected ratio (o/e) 0.96, 90% interval 0.92 to 1.01. Synonymous variants: 569 observed, 576.95 expected, observed/expected ratio (o/e) 0.99, 90% interval 0.92 to 1.06.
Homologues: Orthologues: chimpanzee ALPK1 (98% identical), macaque ALPK1 (94% identical), dog ALPK1 (80% identical), pig ALPK1 (79% identical), rabbit ALPK1 (75% identical), mouse Alpk1 (72% identical), rat Alpk1 (71% identical), guinea pig ALPK1 (57% identical), tropical clawed frog alpk1 (50% identical). Paralogues in human: ALPK2 (18% identical), HSPA12A (7% identical), HSPA12B (7% identical), EEF2K (6% identical).
Diseases named in the same sentence as ALPK1 in open-access papers:
ALPK1 is named in the same sentence as 77 diseases in open-access papers, as found by Europe PMC text mining. Sharing a sentence is not in itself a finding about the gene and the disease. The quoted sentences say what the papers report.
ROSAH syndrome (15 papers, 2019 to 2025). "Whole-exome sequencing analysis of the proband and asymptomatic parental controls revealed a de novo heterozygous ALPK1 variant (NM_025144: c.710C>T, p.Thr237Met), consistent with the clinical phenotype of ROSAH syndrome." (PMID 41235249, 2025). "Through these evaluations, our study aims to deepen the understanding of the mechanisms by which ALPK1 mutations disrupt immune homeostasis and to provide insights for improving early diagnosis and precision management of ROSAH syndrome." (PMID 41235249, 2025). "Clinical manifestations and treatment of ROSAH Syndrome caused by ALPK1 mutations were summarized by literature review." (PMID 41235249, 2025). "To date, approximately 70 cases of ROSAH syndrome have been reported worldwide, most associated with one of four recurrent hotspot mutations in ALPK1, and exhibit overall consistent phenotypes, with some variability in clinical presentation." (PMID 41235249, 2025). "The licensing effect of IFN-γ was also confirmed in primary human monocytes from ROSAH syndrome patients displaying the ALPK1 p.T237M variant." (PMID 39868044, 2025). "This case links a de novo ALPK1 mutation to constitutive NF-κB activation and immune dysfunction in ROSAH syndrome." (PMID 41235249, 2025). "ROSAH syndrome is a rare autosomal dominant disorder caused by heterozygous missense mutations in the ALPK1 gene." (PMID 41235249, 2025). "In a mouse model of ROSAH syndrome generated through the knock-in of heterozygous human ALPK1 harboring the p.T237M mutation, DF-003 inhibits upregulation of inflammatory cytokines in the retina, optic nerve, and cerebral cortex." (PMID 40925900, 2025). "ROSAH syndrome is a rare auto-inflammatory disorder caused by pathogenic mutations in the ALPK1 gene, which result in constitutive activation of the ALPK1-TIFA-NF-κB signaling pathway." (PMID 41235249, 2025). "In this study, we comprehensively evaluated the clinical, and immunological profiles of a 12-year-old boy carrying a de novo ALPK1 mutation and presenting with manifestations consistent with ROSAH syndrome." (PMID 41235249, 2025). "Whole exome gene sequencing identified a shared heterozygous mutation in the ALPK1 gene c.710C>T, consistent with ROSAH syndrome." (PMID 40201710, 2025). "Retinal dystrophy, optic nerve oedema, splenomegaly, anhidrosis and migraine headache (ROSAH) syndrome is an autosomal dominant disorder and to date is known to be caused by either the Thr237Met or Tyr254Cys variant in the protein kinase ALPK1." (PMID 39626775, 2024). "Here, we report on the identification of an additional family with ROSAH syndrome caused by a new Ser277Phe variant in ALPK1 and characterize its effect on ALPK1 activity." (PMID 39626775, 2024). "Retinal dystrophy, optic nerve oedema, splenomegaly, anhidrosis and migraine headache (ROSAH) syndrome is an autosomal dominant disease caused by pathogenic variants in ALPK1." (PMID 39626775, 2024). "The associations of mutations in the ALPK1 gene with inflammatory syndromes and cancer, especially the ROSAH syndrome (the T237M and the Tyr254Cys mutant) and spiradenoma/spiradenoma (the V1092A mutant), were revealed recently." (PMID 37317291, 2023). "We propose that the loss of the specificity of ALPK1 for bacterial ADP-heptose underlies ROSAH syndrome and spiradenoma/spiradenocarcinoma caused by ALPK1 mutation." (PMID 38060563, 2023). "Mutations in the atypical protein kinase ALPK1 (alpha-protein kinase 1) cause two human diseases, ROSAH syndrome and spiradenoma/spiradenocarcinoma." (PMID 38060563, 2023). "This cohort study systematically evaluated 27 patients with ROSAH syndrome for inflammatory features and investigated the effect of ALPK1 mutations on immune signalling." (PMID 35868845, 2022). "The ultimate goal would be discover new variants in new genes in all those patients mutation-negative for genes already found mutated, as was demonstrated for ALPK1 and ROSAH syndrome." (PMID 35883675, 2022).
ROSAH syndrome (continued). "Consistent with the observations in patients with ROSAH syndrome, knock-in mice with the Alpk1 T237M mutation had elevated serum levels of CXCL1, CXCL10 and CCL2." (PMID 35868845, 2022). "ROSAH syndrome is an autoinflammatory disease caused by gain-of-function mutations in ALPK1 and some features of disease are amenable to immunomodulatory therapy." (PMID 35868845, 2022). "Our findings show that ROSAH syndrome is a distinctive autosomal dominant retinal dystrophy syndrome, caused by a recurrent heterozygous variant in ALPK1, and indicate a role for ALPK1 across several different organ systems." (PMID 30967659, 2019). "The known pathogenic variants in ALPK1, particularly those that lead to a gain of function, result in persistent activation of the NF-κB pathway, contributing to the broad spectrum of inflammatory symptoms seen in ROSAH syndrome." (PMID 41269507, 2025). "This study performed an integrated evaluation of clinical manifestations, genetic alterations, and immunological profiles in a pediatric ROSAH syndrome case harboring an ALPK1 mutation, with the objective of dissecting its putative immune-mediated pathogenesis." (PMID 41235249, 2025). "Because ROSAH syndrome results from constitutive ALPK1 activation, it uniquely provides causal insights into the consequences of chronic ALPK1 signaling in humans and reveals previously unrecognized interactions with other innate pathways, including the STING axis." (PMID 40631099, 2025). "Mutations in ALPK1 can also lead to a monogenic multisystem disease termed ROSAH syndrome." (PMID 39868044, 2025). "In addition to the previously reported ALPK1 Thr237Met mutation causing ROSAH syndrome, Tyr254Cys, Thr159Met, and Ser277Phe mutations have also been demonstrated to induce this syndrome." (PMID 41235249, 2025). "The characterization of ALPK1 variants that cause ROSAH syndrome suggests ways in which drugs that selectively inhibit these disease-causing variants may be developed." (PMID 39626775, 2024). "ROSAH syndrome (retinal dystrophy, optic nerve edema, splenomegaly, anhidrosis, and migraine headache) is an autosomal dominant genetic disorder caused by specific mutations in ALPK1." (PMID 39600975, 2024). "This suggested that activation of ALPK1[Thr237Met] by one or more human sugar nucleotides may cause chronic activation of ALPK1 in cells and underlie autoinflammation in ROSAH syndrome." (PMID 39626775, 2024). "ROSAH syndrome (retinal dystrophy, optic nerve edema, splenomegaly, anhidrosis, migraine headache) is an autosomal dominant condition caused by a missense mutation in the ALPK1 gene which was identified in five families." (PMID 36800925, 2023). "Although the initial report of ROSAH syndrome emphasised the visual manifestations associated with the disease, our work additionally establishes ROSAH syndrome as a disease of systemic inflammation caused by gain-of-function mutations in the innate immune receptor ALPK1." (PMID 35868845, 2022). "Two additional unrelated families with ROSAH syndrome were identified (family 4 [Virginia] and family 5 [Delaware]), and affected members were found to be heterozygous for the ALPK1, (c.710C>T, [p.Thr237Met]) variant, which arose de novo in the Delaware patient." (PMID 30967659, 2019). "Here, we investigated ALPK1 signaling in peripheral blood mononuclear cells (PBMCs) to decipher the regulation of the pathway in different cell types, understand the underlying mechanisms, and assess the therapeutic potential of drugs targeting these mechanisms for ROSAH syndrome’s patients." (PMID 39868044, 2025). "The findings from this large, international cohort study provide valuable insights on the clinical spectrum of disease associated with mutations in ALPK1 and highlight the possibility that patients with ROSAH syndrome may be currently unrecognised in cohorts of more common inflammatory disorders." (PMID 35868845, 2022).
ROSAH syndrome (continued). "Several clinical features of ROSAH syndrome, including short dental roots as well as the aberrant production of sweat, breast milk and saliva are not classically associated with inflammation but may reflect ALPK1’s role in ciliary functioning." (PMID 35868845, 2022). "In summary, we name this autosomal dominant condition ROSAH syndrome to reflect the most common features across affected individuals: retinopathy, optic nerve edema, splenomegaly, anhidrosis, and headache, and identify p.Thr237Met ALPK1 as the causative variant." (PMID 30967659, 2019). "With the discovery of the potent, selective ALPK1 inhibitor DF-003, there is also the potential to further interrogate ALPK1 biology in ROSAH syndrome through ex vivo analyses of patient-derived cells, mouse model experiments, and human clinical trials." (PMID 40925900, 2025). "ROSAH syndrome, characterized by constitutive ALPK1 activation, offers a unique window into the in vivo consequences of this signaling axis." (PMID 40631099, 2025). "Heterozygosity for ALPK1, p.Thr237Met leads to ROSAH syndrome, an autosomal dominant ocular systemic disorder." (PMID 30967659, 2019). "Utilizing different genomic technologies and analysis pipelines, we link the disease-causing variant in ALPK1 (ɑ-kinase 1 [MIM 607347], c.710C>T, [p.Thr237Met]) to ROSAH syndrome in all five families." (PMID 30967659, 2019). "Importantly for the treatment of ROSAH syndrome, DF-003 was also able to suppress ALPK1[T237M] activity in biochemical and cell-based assays." (PMID 40925900, 2025). "In contrast, disease-causing mutations in ALPK1 that cause ROSAH syndrome or spiradenoma allow ALPK1 to be activated in cells in the absence of bacterial infection (i.e., without ADP-heptose)." (PMID 39600975, 2024). "Given ALPK1’s role as an innate immune sensor, we hypothesised that ROSAH syndrome is an autoinflammatory disease." (PMID 35868845, 2022). "Additionally, we observed higher mRNA expression of ALPK1 and increased expression of NF-κB regulated genes in RNAseq data from patients with ROSAH syndrome." (PMID 35868845, 2022). "Patients with ROSAH syndrome also exhibited anhidrosis, so the role of ALPK1 in maintenance of epithelial cell polarity may also be relevant for normal function of the sweat glands." (PMID 30967659, 2019). "While our mice thus more closely mimic the heterozygous presentation of human ROSAH syndrome patients, the more muted effects of a single copy of human ALPK1[T237M] may have translated to serum chemokine production at levels below the limits of detection for our ELISAs." (PMID 40925900, 2025).
gout (13 papers, 2015 to 2023). A condition characterized by painful swelling of the joints, which is caused by deposition of urate crystals. "ALPK1 has also been implicated in gout, diabetes, and chronic kidney disease, which are thought to be associated with breast, lung, colorectal, urinary tract, pancreatic, and endometrial cancers and lymphoblastic leukemia." (PMID 36139553, 2022). "ALPK1 is also strongly associated with gout, chronic kidney disease, and diabetes, which are considered as inflammatory diseases and associated with cancer." (PMID 36139553, 2022). "ALPK1 is associated with cancer, gout, chronic kidney disease, and diabetes in humans, animals, and cellular models; they also have common missense variants and higher protein and mRNA expression of ALPK1, suggesting a strong relationship." (PMID 36139553, 2022). "An exception is a study in which only one variant (rs11726117; M861T) of ALPK1 was used to investigate the link between ALPK1 and gout." (PMID 36139553, 2022). "A genomic study analyzed the epistasis of ALPK1 to the urate transporter genes loci and found a positive predictive value (>80%) for gout risk, supporting the role of ALPK1 in causing gout." (PMID 36139553, 2022). "Rs11726117and rs231247 of the ALPK1 gene were associated with gout in a study including a Taiwan aborigines cohort and a Han Chinese cohort." (PMID 30123371, 2018). "For instance, three SNPs (rs11726117, rs231247 and rs231253) in ALPK1 gene located in chromosome 4q21–31 were reported to be significantly associated with gout in Taiwanese populations." (PMID 27506295, 2016). "ALPK1 gene locates in a gout-susceptibility locus (between microsatellite markers 4DS3243 and 4DS1625) on chromosome 4q21–31." (PMID 25326865, 2015). "In the present study, we therefore investigated the association between gout and ALPK1 with Japanese gout cases and controls." (PMID 25326865, 2015). "In the previous genetic study of Taiwanese populations, 3 single nucleotide polymorphisms (SNPs), rs11726117, rs231247 and rs231253, in ALPK1 gene were reported to have a significant association with gout." (PMID 25326865, 2015). "In the Taiwanese populations, ALPK1 was previously reported to be associated with gout susceptibility." (PMID 25326865, 2015). "However, the rs2074379 (M732I) and rs2074388 (G565D) ALPK1 variants were significantly associated not only with the prevalence of type 2 diabetes but also with chronic kidney disease and gout." (PMID 37317291, 2023). "Moreover, colon cancer, gout, chronic kidney disease, and diabetes share common missense variants of ALPK1, indicating that these diseases are closely related." (PMID 36139553, 2022). "However, association analysis did not detect a significant association between rs11726117 (M861T) ALPK1 variant and gout susceptibility in the Japanese population." (PMID 36139553, 2022). "The ABCG2, SLC22A12, and ALPK1 genes have been strongly associated with dysfunction of urate metabolism in patients with gout, but it is unknown how these transporters are expressed in patients with acute or chronic gout." (PMID 35505381, 2022). "Natsuko revealed that ALPK1 mRNA expression is associated with hypertension and creatinine, uric acid (hyperuricemia), and C-reactive protein levels, also supporting the role of ALPK1 in triggering gout." (PMID 36139553, 2022). "However, a missense mutation, rs2074388 (G565D), at the exon 11 of ALPK1 in colon cancer tissues has also been identified in gout, chronic kidney disease, and diabetes." (PMID 36139553, 2022). "Using logistic regression models adjusted for age, gender, body mass index, hypertension, hyperuricemia, cholesterol level, triglyceride level, creatinine level, and alcohol use, they discovered that several variants of ALPK1 were associated with gout risk in independent and pooled analyses." (PMID 36139553, 2022). "ALPK1 is associated with chronic kidney disease, gout and type 2 diabetes mellitus." (PMID 31557402, 2019).